TUBGCP2 (tubulin gamma complex component 2)
Description:
Component of the gamma-tubulin ring complex (gTuRC) which mediates microtubule nucleation. The gTuRC regulates the minus-end nucleation of alpha-beta tubulin heterodimers that grow into microtubule protafilaments, a critical step in centrosome duplication and spindle formation. Plays a role in neuronal migration.
Synonyms: GCP-2; hGCP2; h103p; hSpc97; GCP2; Spc97p; SPBC97; ALP4; Grip103; PAMDDFS; SPC97
Tractability: Small molecule: a structure with a bound ligand is known. PROTAC: ubiquitination databases record sites on it; its protein half-life has been measured.
Gene: Protein-coding gene on chromosome 10 (133,278,635 to 133,318,823, reverse strand). Ensembl gene ENSG00000130640.
Subcellular location: Cytoplasm, cytoskeleton, microtubule organizing center, centrosome
Subcellular location (Human Protein Atlas): Basal body; Centrosome; Nucleoplasm
Pathways (Reactome):
Cell Cycle: Recruitment of NuMA to mitotic centrosomes; Recruitment of mitotic centrosome proteins and complexes
Gene Ontology:
Molecular function: protein binding; gamma-tubulin binding; microtubule minus-end binding
Biological process: brain development; neuron migration; meiotic cell cycle; microtubule nucleation; mitotic cell cycle; protein-containing complex assembly; spindle assembly; microtubule cytoskeleton organization
Cellular component: centrosome; membrane; microtubule organizing center; cytoplasmic microtubule; cytosol; gamma-tubulin complex; spindle pole
Genetic constraint (gnomAD): Loss-of-function variants: 56 observed, 91.78 expected, observed/expected ratio (o/e) 0.61, 90% interval 0.49 to 0.76. The upper end of that interval is the gene's LOEUF score, 0.76, which puts it in group 3 of 6, group 1 being the genes least tolerant of losing a copy. Missense variants: 1,093 observed, 1,206.5 expected, observed/expected ratio (o/e) 0.91, 90% interval 0.86 to 0.95. Synonymous variants: 533 observed, 509.58 expected, observed/expected ratio (o/e) 1.05, 90% interval 0.97 to 1.12.
Homologues: Orthologues: macaque TUBGCP2 (94% identical), chimpanzee TUBGCP2 (92% identical), guinea pig TUBGCP2 (92% identical), rat Tubgcp2 (91% identical), mouse Tubgcp2 (91% identical), dog TUBGCP2 (91% identical), rabbit TUBGCP2 (90% identical), pig TUBGCP2 (89% identical), tropical clawed frog tubgcp2 (77% identical), zebrafish tubgcp2 (77% identical), Drosophila melanogaster Grip84 (32% identical), Drosophila melanogaster t-Grip84 (22% identical). Paralogues in human: TUBGCP3 (25% identical), TUBGCP6 (20% identical), TUBGCP5 (14% identical), TUBGCP4 (14% identical).
Diseases named in the same sentence as TUBGCP2 in open-access papers:
TUBGCP2 is named in the same sentence as 19 diseases in open-access papers, as found by Europe PMC text mining. Sharing a sentence is not in itself a finding about the gene and the disease. The quoted sentences say what the papers report.
Pachygyria (4 papers, 2021 to 2025). Pachygyria is a malformation of cortical development with abnormally wide gyri with sulci 1,5-3 cm apart and abnormally thick cortex measuring more than 5 mm (radiological definition). "The gene TUBGCP2 is also of a particular interest, since it is related to the neurological condition of pachygyria, microcephaly, developmental delay, and dysmorphic facies, with or without seizures (OMIM 618737) with an autosomal recessive mode of inheritance." (PMID 40988857, 2025). "Brain MRI findings indicate that TUBGCP2-related LIS spectrum disorders exhibit distinctive neuroradiological features, including microcephaly and LIS (agyria, pachygyria, and SBH)." (PMID 40017707, 2025).
developmental delay (3 papers, 2022 to 2025). "In human microcephaly patients carrying bi-allelic TUBGCP2 (or other TUBCGP) mutations, developmental delays are usual, however anatomical defects, other than microcephaly, are less obvious and are generally more apparent on a cellular scale." (PMID 36078134, 2022).
microcephaly (3 papers, 2022 to 2025). A congenital or acquired developmental disorder in which the circumference of the head is smaller than normal for the person's age and sex. "We present an alternative simple vertebrate/invertebrate dual system to investigate fundamental TUBGCP2-related processes driving human microcephaly and associated developmental traits." (PMID 36078134, 2022). "In these, we examine cellular and phenotypic effects of depleting the respective homologs of TUBGCP2, a constituent of the most fundamental of cellular machineries, for which bi-allelic mutations in humans results in microcephaly." (PMID 36078134, 2022). "Microcephaly presents in neurodevelopmental disorders with multiple aetiologies, including bi-allelic mutation in TUBGCP2, a component of the biologically fundamental and conserved microtubule-nucleation complex, γ-TuRC." (PMID 36078134, 2022). "Microcephalic zebrafish larvae treated with TUBGCP2–mRNA-specific MOs also display a slight but significant reduction in body length, correspondent to the degree of microcephaly developed, reflected in the Microcephaly Index." (PMID 36078134, 2022).
Lissencephaly (2 papers, 2023 to 2025). A spectrum of malformations of cortical development caused by insufficient neuronal migration that subsumes the terms agyria, pachygyria and subcortical band heterotopia. "Our study expands the genotype of this brain malformation disorder associated with TUBGCP2 variants by presenting the first case of TUBGCP2 variants causing lissencephaly spectrum disorders in China." (PMID 40017707, 2025). "A literature search revealed seven patients with lissencephaly spectrum disorders associated with TUBGCP2 variants, including eight gene variation types." (PMID 40017707, 2025). "Clinical and genetic data of a patient diagnosed with TUBGCP2-related lissencephaly spectrum disorder at the Department of Pediatric Neurology, Shengjing Hospital, in March 2022 were collected." (PMID 40017707, 2025).
autosomal recessive primary microcephaly (1 paper, 2022). Autosomal recessive primary microcephaly (MCPH) is a rare genetically heterogeneous disorder of neurogenic brain development characterized by reduced head circumference at birth with no gross anomalies of brain architecture and variable degrees of intellectual impairment. "Bi-allelic mutation in any of at least 20 human genes, including TUBGCP2, causes autosomal recessive primary microcephaly (MCPH); most of these genes encode microtubule or microtubule-associated proteins." (PMID 36078134, 2022).
cardiomyopathy (1 paper, 2025). A disease of the heart muscle or myocardium proper. "Downregulated proteins in the aged group (TUBGCP2 and SLC25A11) were enriched in cytoskeletal dynamics and cardiomyopathy pathways, whereas upregulated proteins (ATP6V0D2 and TPM1) associated with oxidative stress and neurodegenerative disorders." (PMID 40662159, 2025). "Prominently downregulated proteins (TUBGCP2, NPR2, MT-ATP6, SLC25A11, and so on) were enriched in cytoskeletal dynamics and cardiomyopathy pathways, while upregulated proteins (ATP6V0D2, HNRNPA1, TPM1, and so on) associated with oxidative stress responses and neurodegenerative disorders (AD and PD)." (PMID 40662159, 2025).
epilepsy (1 paper, 2021). A brain disorder characterized by episodes of abnormally increased neuronal discharge resulting in transient episodes of sensory or motor neurological dysfunction, or psychic dysfunction. "We describe two siblings from a consanguineous Turkish family with dysmorphic features, developmental delay, brain malformation, and epilepsy carrying a homozygous mutation (p.Glu311Lys) in TUBGCP2 encoding the γ-tubulin complex 2 (GCP2) protein." (PMID 33458610, 2021).
glioma (1 paper, 2025). A benign or malignant brain and spinal cord tumor that arises from glial cells (astrocytes, oligodendrocytes, ependymal cells). "Moreover, it has been shown that TUBGCP2 and TUBGCP3 are overexpressed in glioma." (PMID 40073758, 2025).
lung carcinoma (1 paper, 2025). "The protein with the strongest interaction to our new drug candidate was TUBGCP2 which was identified before in a genetic synthetic lethality screen as a sensitivity gene for paclitaxel in lung cancer." (PMID 40073758, 2025).
cancer (3 papers, 2015 to 2023). A tumor composed of atypical neoplastic, often pleomorphic cells that invade other tissues. "Except for 3 pseudogenes (GUCY1B2, HNRNPA1P33, and TUBA3FP), all of the remaining 15 genes showed the most involvement as tumor suppressor genes in distinct carcinomas, and four genes (TUBGCP2, PLEC, CLEC11A, and BARD1) were associated with AML." (PMID 29299160, 2017).
tumor (3 papers, 2018 to 2023). "Analyzing expression profile of BC tumors and tumor-adjacent normal breast tissues showed upregulation of TUBA1A, TUBA1C, TUBB and TUBB3 and downregulation of TUBB2A, TUBB2B, TUBB6, TUBB7P pseudogene, and TUBGCP2 in the tumor tissues compared to the normal breast tissues." (PMID 30126203, 2018).
adenocarcinoma (1 paper, 2015). A common cancer characterized by the presence of malignant glandular cells. "Previous studies by others have indicated that silencing of ACRBP (testis cancer antigen) or TUBGCP2 (microtubule-associated protein) did not affect cell viability but did enhance taxol-induced mitotic arrest in H1299 and H2126 cells (NSCLC, adenocarcinomas)." (PMID 26086592, 2015).
TUBGCP2 also shares sentences with these, for which no sentence is quoted: neurodevelopmental disorder (2 papers); brain malformation (1); brainstem atrophy (1); hepatocellular carcinoma (1); ovarian carcinoma (1); subcortical band heterotopia (1); tubulinopathy (1).